IL24 (interleukin 24)
Diseases named in the same sentence as IL24 in open-access papers (continued):
Sharing a sentence is not in itself a finding about the gene and the disease.
pulmonary tuberculosis (5 papers, 2019 to 2023). A bacterial infection that affects the lungs and is caused by Mycobacterium tuberculosis. "While the role of IL-20 cytokines in TB is poorly investigated, one report demonstrated that IL-19 and IL-24 are elevated in pulmonary TB patients and in vitro neutralization of these cytokines resulted in an enhanced CD4+ Th1/Th17 responses." (PMID 38162636, 2023). "The T cells of patients with lymphatic filariasis or pulmonary tuberculosis expressed high levels of IL-24, suppressing Th1 and Th17 cells into producing their signature cytokines, IFN-γ and IL-17A, respectively." (PMID 36233291, 2022). "Similarly, the increased expression of IL-19 and IL-24 in active pulmonary tuberculosis patients also mediated decreased expression of Th1/Tc1 and Th17/Tc17 cytokine in CD4+ and CD8+ T cells." (PMID 31921658, 2019). "Our study identified unique gene signatures (IL-27, STAT1, IRF1, TLR4, IL-15, IL-2RA, IL-24, TGFβ, CD28, CD80, NFATC1, and PTGDR2) that discriminate active pulmonary TB from uninfected controls using unstimulated PBMCs." (PMID 37460564, 2023).
ulcerative colitis (5 papers, 2016 to 2023). An inflammatory bowel disease involving the mucosal surface of the large intestine and rectum. "IL-20, IL-22, and IL-24 have been found to be higher in the colons of patients with ulcerative colitis, where mucosal epithelial damage is very common." (PMID 31311100, 2019). "It has been found that the expression levels of IL-20, IL-22, and IL-24 are higher in the colon of patients with ulcerative colitis but that their roles in colonic epithelial renewal are not clearly understood." (PMID 31311100, 2019). "The interleukin (IL)-20 subfamily of cytokines consists of IL-19, IL-20, IL-22, IL-24, and IL-26, and the expression of IL-20, IL-22, and IL-24 is reported to be higher in the colon of patients with ulcerative colitis." (PMID 31311100, 2019). "More recently, a clinical study demonstrated expression of IL-19 and IL-24 at the gene and protein expression levels in tissue and peripheral cells of patients exhibiting active or inactive Crohn’s Disease (CD) or active or inactive ulcerative colitis (UC)." (PMID 27271601, 2016). "In addition, cells producing IL-24 and IL-19 were increased in active Crohn’s Disease patients in comparison to control patients and those with active ulcerative colitis." (PMID 27271601, 2016).
Arthritis (4 papers, 2013 to 2025). Inflammation of a joint. "The potential of IL24 as a therapeutic target, demonstrated in a murine collagen-induced arthritis model through IL-20 receptor blockade, presents a promising avenue for intervention in OA." (PMID 38792924, 2024). "In the context of arthritis, it is intriguing that IL-20 has also been reported as a driver of osteoporosis and that both IL-19 and IL-24 had roles in a rat model of bone resorption." (PMID 26968800, 2016). "Expression of IL-19, IL-20, and IL-24 in both monocytes/macrophages and fibroblast-like synovial cells has been reported in arthritis." (PMID 26968800, 2016). "In conclusion, this study establishes an IL-24 sandwich ELISA system and validates it for measuring plasma from arthritis patients with a simple set of validation steps." (PMID 23875127, 2013). "EDTA plasma was superior to heparin plasma and serum when meassuring the concentration of IL-24 in arthritis blood samples." (PMID 23875127, 2013). "Thus, to identify false positive results plasma samples from patients with arthritis were both measured in wells coated with anti-IL-24 specific antibody and in wells coated with isotype matched control antibody in an identical concentration." (PMID 23875127, 2013). "This study establishes a simple set of steps to validate and optimize a sandwich ELISA before using it for measuring plasma from arthritis patients using an anti-IL-24 sandwich ELISA system as an example consisting of a mouse capture antibody and a goat detection antibody." (PMID 23875127, 2013).
inflammatory skin disease (4 papers, 2013 to 2025). Inflammatory skin disorders covers a broad category that includes many conditions ranging in severity, from mild itching to grave medical health complications These disorders are common in people of all ages and races. "Since IL-24 is involved in the pathogenesis of inflammatory skin diseases and since it is induced by IL-6, we further characterized the effect of R7 on IL-6 and IL-24 expression and secretion." (PMID 40461723, 2025).
liver fibrosis (4 papers, 2020 to 2025). "Our results are in line with the previous observations implying the role IL-19 in intestinal and the role of IL-24 in liver fibrosis and wound healing." (PMID 32306980, 2020). "Although research beyond oncology remains limited, studies have demonstrated that in acute and chronic liver injury models, IL-24 protects hepatocytes, inhibits Ly6C + monocyte recruitment, and alleviates liver fibrosis by suppressing hepatic stellate cell activation and proliferation." (PMID 41288708, 2025). "We confirmed that there were no expression changes associated with liver fibrosis in the mRNA expression levels of IL-20, IL-24, and IL-20R1." (PMID 37509702, 2023).
metastatic disease (4 papers, 2010 to 2021). "The results of the study revealed that DOTAP:chol (DOTAP:Cholesterol) nanoparticles efficiently deliver mda-7/IL-24 to human lung tumor xenografts, resulting in growth suppression in both primary and metastatic tumors and they also inhibited tumor angiogenesis." (PMID 35008495, 2021). "In principle, a combination of a BH3 mimetic, such as BI-97D6 with more pronounced Bcl-2/Mcl-1 inhibitory activity, with a CRCA such as Ad.tCCN1-CTV-m7 expressing a systemically active cytokine, mda-7/IL-24, should elicit profound efficacy toward both primary and metastatic tumors in the clinic." (PMID 25926554, 2015).
metastatic melanoma (4 papers, 2007 to 2025). A melanoma that has spread from its primary site to another anatomic site. "More recently plans for a Phase I clinical trial testing systemic IL-24 nanocarrier therapy for metastatic melanoma is underway." (PMID 21490751, 2011). "Similarly, IL-24 nanocarrier therapy can be combined with Raf-targeted inhibitor (sorafenib) or alternatively with the chemotherapeutic Temozolomide for treatment of metastatic melanoma." (PMID 21490751, 2011).
tuberculosis (4 papers, 2013 to 2025). A chronic, recurrent infection caused by the bacterium Mycobacterium tuberculosis. "In comparison to individuals with latent tuberculosis infection, peripheral blood mononuclear cells (PMBCs) from tuberculosis patients had lower levels of IL-24 and IFN-γ." (PMID 27271601, 2016). "Whereas analysis of fold-induction showed significant induction of IL-19, IL-20, IL-24, and IL-26 by M. tuberculosis, the differences detected between the tuberculosis-IRIS and non-IRIS groups were neither great nor statistically significant." (PMID 23303806, 2013). "Although IL-24 tended to be more induced in cultures for the non-IRIS group at both time points, the difference between the tuberculosis-IRIS and non-IRIS groups was not significant." (PMID 23303806, 2013). "Significantly higher transcript levels were observed for IL-22 in tuberculosis-IRIS patients after stimulation (P = .009), whereas levels of IL-24 transcripts were higher for non-IRIS patients (P = .020)." (PMID 23303806, 2013). "In PBMCs from both tuberculosis-IRIS and non-IRIS patients, M. tuberculosis stimulation resulted in increased transcript abundance for many of the cytokines, most prominently IL-19, IL-20, IL-24, and IL-26." (PMID 23303806, 2013).
viral infections (4 papers, 2020 to 2025). "Our fluorescence microscopy, transmission electron microscopy, and Western blot results demonstrated the successful viral infection and production of exogenous IL-24 in A375 cells." (PMID 33257647, 2020). "The direct killing pathway plays a decisive role in A375-bearing immunodeficient mouse model, while playing no role in B16-bearing immunocompetent mouse model for the inability of successful viral infection and exogenous IL-24 expression in B16 cells." (PMID 33257647, 2020). "The role of IL-24 in host defense against viral infections remains incompletely understood." (PMID 40943325, 2025). "To determine whether the antitumor efficacy of ZD55-IL-24 in A375-bearing immunocompromised mouse model depended mainly on the direct killing pathway rather than antitumor immunity pathway, we first examined the viral infection and exogenous IL-24 expression in A375 cells in vitro." (PMID 33257647, 2020).
atherosclerosis (3 papers, 2016 to 2023). A disease characterized by the build-up of fatty material and calcium deposition in the arterial wall resulting in partial or complete occlusion of the arterial lumen. "IL-24 has been shown to suppress calcification and osteoblast marker expression to promote the growth of vascular smooth muscle cells, which associates it to the pathogenesis of atherosclerosis." (PMID 27271601, 2016). "Instead, the combined effect of intermittent hypoxia and IL-1β treatment led to the most pronounced expression of IL-19, IL-24 and IL-32 which are known to be dysregulated in inflammatory disorders, such as atherosclerosis." (PMID 37753073, 2023). "Another report showed that IL‐24 inhibited normal vascular smooth muscle cells (VSMCs) growth by inhibiting the H2O2‐induced production of reactive oxygen species (ROS) and the expression of antioxidant enzymes, and VSMCs are the main actors of atherosclerosis." (PMID 34132454, 2021).
coeliac disease (3 papers, 2020 to 2026). "Although its role has been investigated in other intestinal conditions like IBD, and Coeliac Disease, the role of IL-24 towards the pathogenesis of NEC still needs to be further investigated." (PMID 41602873, 2026). "Previously, in accordance with our present results we demonstrated that TGFβ treatment decrease the IL-24 expression of PBMCs derived from children with coeliac disease." (PMID 32306980, 2020).
colorectal adenocarcinoma (3 papers, 2019 to 2025). The most common type of colorectal carcinoma. "But the role of direct regulatory activity of IL-24 to tumor-infiltrating T cells in colorectal adenocarcinoma patients still needed further elucidation." (PMID 31921658, 2019). "The current results suggested an important immunomodulatory function of IL-24 to T cells in a dose-dependent manner in colorectal adenocarcinoma." (PMID 31921658, 2019). "In conclusion, down-regulation of circulating and tissue-resident IL-24 in colorectal adenocarcinoma was inadequate for developing anti-tumor activity." (PMID 31921658, 2019). "We firstly screened the protein and mRNA expression profile of IL-24 in colorectal adenocarcinoma patients." (PMID 31921658, 2019). "This was consistent with our present findings, which indicated a robust decline of IL-24 in colorectal adenocarcinoma tissues, as well as in peripheral and tumor-infiltrating T cells from colorectal adenocarcinoma patients." (PMID 31921658, 2019). "This indicated that high concentration of IL-24 mainly influenced perforin/granzyme B pathway for cytolytic function of CD8+ T cells in colorectal adenocarcinoma." (PMID 31921658, 2019). "IL-24 was decreasingly expressed in both peripheral bloods and cancer tissues in colorectal adenocarcinoma patients." (PMID 31921658, 2019). "Furthermore, IL-24 mRNA was also investigated in tumor tissue and tumor-infiltrating T cells from colorectal adenocarcinoma patients." (PMID 31921658, 2019). "CD8+ T cells, which were purified from twelve HLA-A2 restricted colorectal adenocarcinoma patients, were stimulated with recombinant IL-24 for 24 h, and were then co-cultured with CACO-2 cells (effector: target = 1: 5) in both direct contact and indirect contact manner." (PMID 31921658, 2019). "Collectively, reduced expression of circulating and tissue-resident IL-24 might contribute to pathogenesis and progression of colorectal adenocarcinoma." (PMID 31921658, 2019). "IL-24 mRNA expression was also notably down-regulated in both peripheral CD4+ and CD8+ T cells from colorectal adenocarcinoma patients when compared with those from healthy individuals (Student's t-tests, all P < 0.0001)." (PMID 31921658, 2019). "In contrast, high concentration of IL-24 robustly promoted CD4+ T cell proliferation, enhanced Th1 and Th17 response, and inhibited Treg response in colorectal adenocarcinoma patients." (PMID 31921658, 2019). "High-concentration of IL-24 promoted peripheral and tumor-infiltrating CD4+ and CD8+ T cell function, which provided novel therapeutic approaches to colorectal adenocarcinoma." (PMID 31921658, 2019). "In the current study, IL-24 was decreasingly expressed in both peripheral bloods and cancer tissues in colorectal adenocarcinoma, but did not correlate with either histological differentiation or TNM staging." (PMID 31921658, 2019). "High-concentration of IL-24 might promote anti-tumor immune responses in development novel therapeutic approaches to colorectal adenocarcinoma." (PMID 31921658, 2019). "However, high concentration of IL-24 also notably increased CD8+ T cell proliferation, and elevated perforin/granzye B, but not FasL expression in CD8+ T cells from peripheral and tumor-infiltrating CD8+ T cells from colorectal adenocarcinoma patients." (PMID 31921658, 2019). "Thus, we hypothesized that IL-24 also modulates CD4+ and CD8+ T cell activity in colorectal adenocarcinoma patients in a dose-dependent manner." (PMID 31921658, 2019).
endometriosis (3 papers, 2021 to 2025). The growth of functional endometrial tissue in anatomic sites outside the uterine body. "Recently, altered levels of interleukin-24 (IL-24), a member of the IL-10 cytokine family also known as melanoma differentiation-associated gene-7 (mda-7), have been determined in the endometrium of women with endometriosis." (PMID 40607413, 2025). "IL-24, a member of the IL-10 cytokine family, has also been implicated in the pathogenesis of endometriosis." (PMID 40607413, 2025). "In contrast, the percentages of IL-24–producing immature B cells were lower in the endometriosis group than that in the control group." (PMID 40607413, 2025). "Percentages of Tregs, B10 cells, immature B cells, and plasmablasts that produce IL-24 were measured in the peripheral blood of women with endometriosis (n=24) and healthy women (n=24) using flow cytometry." (PMID 40607413, 2025). "Within the Breg subpopulations, the percentages of IL-24–producing plasmablasts were higher in the overall endometriosis cohort as well as in women with stage IV endometriosis compared with healthy women." (PMID 40607413, 2025). "In this study, we determined the expression of IL-24 in Tregs and selected Breg subpopulations in women with endometriosis compared with healthy women." (PMID 40607413, 2025). "We have shown, for the first time, that Tregs and Bregs secrete IL-24 and that their percentages are altered in endometriosis." (PMID 40607413, 2025). "Using the tSNE algorithm, we visualized IL-24–producing T cells in healthy controls and women with endometriosis." (PMID 40607413, 2025). "Further research is required to elucidate the exact role of IL-24–producing regulatory lymphocytes in the development and progression of endometriosis." (PMID 40607413, 2025). "Here, we also observed a similar trend of increased IL-24+ plasmablast percentages in women with endometriosis compared with the healthy controls." (PMID 40607413, 2025). "We revealed for the first time that circulating regulatory T and B lymphocytes secrete IL-24 and their percentages are altered in women with endometriosis compared with healthy women." (PMID 40607413, 2025). "IL-24 secretion appears to enhance the improper immunosuppressive activity of Tregs and plasmablasts in endometriosis, which enables the implantation and growth of endometrial lesions outside the uterus." (PMID 40607413, 2025). "We observed an increased percentage of IL-24–producing Tregs in the total pool of women with endometriosis and in women with stages III and IV of endometriosis compared to controls." (PMID 40607413, 2025). "First, we visualized the population of IL-24–producing B cells in healthy controls and women with endometriosis using t-distributed stochastic neighbor embedding (tSNE) algorithms." (PMID 40607413, 2025). "Addressing these limitations in future studies will be essential for a deeper understanding of IL-24’s role in the progression of endometriosis, and its potential clinical relevance." (PMID 40607413, 2025). "tSNE analysis, presented as IL-24 heatmaps of different B cell subsets, revealed IL-24 expression in all analyzed clusters and similarity in complexity and distribution of IL-24 expression in healthy controls and women with endometriosis." (PMID 40607413, 2025). "Despite the novel findings on the role of IL-24 in endometriosis, our study has several limitations that should be considered when interpreting the results." (PMID 40607413, 2025). "Dysregulation of proinflammatory cytokines (TNF-alpha, IL6...) or IL24 has been demonstrated to play an important role in the pathophysiology of eutopic and ectopic endometriosis." (PMID 38396681, 2024). "We explored whether Tregs produce IL-24 and whether their percentages change in women with endometriosis." (PMID 40607413, 2025). "However, we observed decreased percentages of IL-24–producing immature B cells in women with endometriosis compared with those in the control group (p < 0.05)." (PMID 40607413, 2025).